PTPRJ (protein tyrosine phosphatase receptor type J)
Diseases named in the same sentence as PTPRJ in open-access papers (continued):
Sharing a sentence is not in itself a finding about the gene and the disease.
glioblastoma (4 papers, 2015 to 2024). The most malignant astrocytic tumor (WHO grade IV). "However, significantly higher upregulation of PTPRJ has been identified in glioblastoma multiforme, indicating a potentially cancer-specific function of PTPRJ." (PMID 38999976, 2024). "In agreement with the anti-proliferative effect of the rat PTPRJ observed in glioblastoma cell lines, the proliferation rate of Ad5-PTPRJ infected cells was reduced compared to Ad5-GFP infected cells; however, there was no change in the proliferation of cells overexpressing sPTPRJ (Ad5-sPTPRJ)." (PMID 28052032, 2017).
hepatocellular carcinoma (4 papers, 2012 to 2022). A malignant tumor that arises from hepatocytes. "An inverse correlation between miR-328 and PTPRJ mRNA levels has also been assessed in hepatocellular carcinoma, where PTPRJ expression negatively correlates with the progression of this malignancy." (PMID 29805737, 2018).
melanoma (4 papers, 2016 to 2024). A malignant, usually aggressive tumor composed of atypical, neoplastic melanocytes. "Another syndecan, SDC2, together with PTPRJ is on top of the R-L-list in the melanocytic module and plays a crucial role in the migratory potential of melanoma cells and metastatic melanoma associated with cachexia, respectively." (PMID 38785552, 2024). "One recent study observed truncating PTPRJ mutations in 23% (7/31) of canine mucosal melanomas, while another study reported truncating mutations in both human (1/30) and canine (2/65) mucosal melanomas." (PMID 35706047, 2022). "We have discovered seven cases (19%) of canine melanomas bearing somatic PTPRJ mutations." (PMID 30188888, 2018). "We have also found a new putative cancer gene, PTPRJ, frequently mutated in canine melanoma." (PMID 30188888, 2018). "In summary, our meta-analyses of 147 acral and 93 mucosal melanomas identified PTPRJ, FER, SKP2, LZTR1, CIC, and PRKN as part of a long tail of driver events that deserves further study and characterization." (PMID 35706047, 2022). "Mutations in the protein tyrosine phosphatase PTPRJ, 5 truncating, 3 missense, and 1 in-frame indel, were identified in 9 melanomas, 4 acral and 5 mucosal, and PTPRJ was homozygously deleted in two additional acral melanomas." (PMID 35706047, 2022).
acute myeloid leukemia (3 papers, 2013 to 2022). Acute myeloid leukemia (AML) is a group of neoplasms arising from precursor cells committed to the myeloid cell-line differentiation. "PTPRJ is a negative regulator of FLT3 signaling that is linked to ROS formation and DNA damage, and deletion of PTPRJ promoted myeloproliferative disease in FLT3-internal tandem duplication acute myeloid leukemia." (PMID 31384238, 2019).
asthma (3 papers, 2018 to 2024). "Genetic inactivation of the PTPRJ gene, which encodes CD148, protected mice from airway hyper-responsiveness in two different asthma models." (PMID 29498714, 2018). "Notable genes that were differentially methylated based on asthma severity included RUNX3, several members of the HLA family, AGT, PTPRC, PTPRJ, and several genes downstream of the JAK2 and TNF signaling pathway." (PMID 39380119, 2024).
atherosclerosis (3 papers, 2014 to 2025). A disease characterized by the build-up of fatty material and calcium deposition in the arterial wall resulting in partial or complete occlusion of the arterial lumen. "As regard to arteriosclerosis, research has pinpointed protein tyrosine phosphatase receptor type J (PTPRJ) and dehydrogenase/reductase 9 (DHRS9) as pivotal biomarkers with high diagnostic accuracy for the pathological process of atherosclerosis." (PMID 40809841, 2025). "In the context of atherosclerosis, vascular injury or inflammation, and tumor angiogenesis, COX-2/PGE2 signaling in endothelial cells is stimulated, which could indicate a major role in regulating PTPRJ expression and enzymatic activity." (PMID 25532119, 2014).
breast tumor (3 papers, 2012 to 2018). "Meta-analysis revealed that the gene encoding PTPRJ is frequently lost in breast tumors and that low expression of the transcript associated with poorer overall survival at 20 years." (PMID 22815804, 2012). "Consistent with this, PTPRJ transcript expression analysis in a tumor library suggests reduced expression in breast tumors compared to normal." (PMID 22815804, 2012). "PTPRJ protein was mislocated in the majority of primary breast tumors, which would most likely result in impaired function of the phosphatase, as concluded by other studies investigating its localisation." (PMID 22815804, 2012). "PTPRJ LOH has, however, been reported in a small number of breast tumors and allele-specific PTPRJ LOH suggests the existence of a putative cancer resistance PTPRJ SNP (A1176C) that is more frequently lost in tumors with PTPRJ LOH." (PMID 22815804, 2012). "Within the same breast tumor specimen, normal apical PTPRJ staining was retained where tubule formation was conserved and was diffuse or cytoplasmic in areas where this architecture was lost." (PMID 22815804, 2012). "More recently, a subclonal K1017N missense mutation in the non-catalytic cytoplasmic domain of PTPRJ was identified in a primary breast tumor with significant enrichment in a brain metastases and patient-derived xenograft." (PMID 30188888, 2018). "Interestingly, comparison of PTPRJ mRNA in tumors derived from each tissue type revealed the greatest relative downregulation in breast tumors (n = 23), followed by stomach, consistent with the literature supporting a tumor suppressive role in these two tissues." (PMID 22815804, 2012).
clear cell renal cell carcinoma (3 papers, 2018 to 2020). "Furthermore, PTPRJ is critical for clear renal cell carcinoma development." (PMID 31384238, 2019).
depression (3 papers, 2021). "PTPRJ encodes a protein of the family of tyrosine phosphatase, and it has been reported as a shared genetic factor of LOAD and major depression disorder." (PMID 34873149, 2021). "The SNP-dietary interactions suggest that PTPRJ and KYNU may play a role in alcohol-induced depression." (PMID 33807197, 2021). "Additionally, several suggestively significant SNP-dietary interactions were observed in depression GWEI, such as interaction between rs117916244 (PTPRJ) and total drinks of alcohol per month, and interaction between rs62169868 (KYNU) and red wine glasses per month." (PMID 33807197, 2021).
glioma (3 papers, 2012 to 2021). A benign or malignant brain and spinal cord tumor that arises from glial cells (astrocytes, oligodendrocytes, ependymal cells). "We excluded four genes (SLCO3A1, C10orf11, PTPRJ, and NMNAT1) from further analysis because the direction of association of additional tested SNPs with glioma risk was inconsistent with our hypothesis." (PMID 23091480, 2012).
myeloproliferative disease (3 papers, 2017 to 2022). "Similarly, the reactivation of PTPRJ’s PTP activity by blocking ROS has been demonstrated to prolong survival in a murine model of FLT3 ITD–driven myeloproliferative disease." (PMID 36452504, 2022). "In addition, activated PTPRJ was shown to inhibit cell transformation in vitro and extend survival of mice in the 32D cell/C3H/HeJ mouse model of FLT3 ITD–driven myeloproliferative disease." (PMID 28858244, 2017).
pancreatic cancer (3 papers, 2018 to 2022). "Our group also demonstrated that virus-mediated PTPRJ overexpression is effective in preclinical models of both thyroid and pancreatic cancer, suggesting that PTPRJ is a proof-of-principle therapeutic gene." (PMID 29805737, 2018).
B-cell lymphomas (2 papers, 2014 to 2022). "From these studies LOH of the protein tyrosine phosphatase receptor type J (PTPRJ) gene was identified as a common event in the lymphomagenesis of these B-cell lymphomas." (PMID 24885312, 2014).
cervical cancer (2 papers, 2022). A primary or metastatic malignant neoplasm involving the cervix. "It was shown that PTPRJ downregulation significantly increased cell viability, growth, and migration rates and the transition from G1 to S phase, and this phenomenon was rescued by the overexpression of PTPRJ in cervical cancer C33A cells." (PMID 36611803, 2022). "PTPRJ may be a suitable target for gene therapy in cervical cancer because it also controls the expression of STAT3 downstream factors such as cyclin D, Bax, VEGF, and MMP2." (PMID 36611803, 2022).
Kawasaki disease (2 papers, 2021 to 2022). A rare inflammatory disease characterized by an acute febrile, systemic, self-limiting, medium-vessel vasculitis primarily affecting children. "The effect of five SNPs that showed to be the most statistically associated with the Kawasaki disease in this study was evaluated, this includes: rs12037447 in non-coding sequence and rs146732504 in KIF25, rs151078858 in PTPRJ, rs55723436 in SPECC1L, rs6094136 in RPN2 genes." (PMID 33692975, 2021).
lung carcinoma (2 papers, 2018 to 2020). "We first validated PTPRJ-CD98hc interaction, then demonstrated that PTPRJ overexpression dramatically reduces CD98hc protein levels in A549 lung cancer cells." (PMID 29805737, 2018). "In the present study we demonstrate that PTPRJ both dephosphorylates and promotes CD98hc ubiquitylation and proteasome degradation and accordingly, that CD98hc protein downregulation is dependent on PTPRJ overexpression in lung cancer cells." (PMID 29805737, 2018). "Moreover, PTPRJ overexpression combined with CD98hc silencing consistently reduced cell proliferation and triggered apoptosis of lung cancer cells." (PMID 29805737, 2018). "First, we validated the interaction between recombinant His6-tagged PTPRJ protein and endogenous CD98hc in A549 lung cancer cells by co-immunoprecipitation experiments; no CD98hc protein was observed in the same assay performed with the PTPRJ protein used as a control." (PMID 29805737, 2018).
Cervical Tumor (1 paper, 2022). "Similar to other cancers, PTPRJ is significantly downregulated in human cervical tumors." (PMID 36611803, 2022).
cholangiocarcinoma (1 paper, 2022). A carcinoma that arises from the intrahepatic biliary tree (intrahepatic cholangiocarcinoma) or from the junction, or adjacent to the junction, of the right and left hepatic ducts (hilar cholangiocarcinoma). "However, P38 inhibits downregulation of Akt and ERK phosphorylation levels, thereby promoting their activity, proliferation, and invasion in cholangiocarcinoma cells, and conversely, PTPRJ has been shown to recognize the receptor PTK Met as a substrate." (PMID 36611803, 2022).
colorectal adenocarcinoma (1 paper, 2012). The most common type of colorectal carcinoma. "For example, PTPRJ, a gene originally identified as a candidate tumor suppressor mapping to the mouse Scc1 locus, was shown to preferentially lose a suspected resistance allele in a subset of heterozygous human colorectal adenocarcinomas showing loss of heterozygosity at PTPRJ." (PMID 22629442, 2012).
esophageal cancer (1 paper, 2019). A primary or metastatic malignant neoplasm involving the esophagus. "Missense polymorphisms of the PTPRJ gene affect susceptibility to a variety of human cancers, including lung, head and neck, colorectal, and esophageal cancers." (PMID 31384238, 2019).
invasive ductal carcinomas (1 paper, 2012). "Although PTPRJ protein expression was detected in all cases, the proportion of positive cells and the distribution of staining were variable, as shown in panels 2D-E depicting different fields of view from the same grade 3 invasive ductal carcinoma." (PMID 22815804, 2012).
mental disorder (1 paper, 2024). A disease that has its basis in the disruption of mental process. "Lastly, we identified 3 novel independent loci (PTPRJ, IBDP, and SUFU) that are associated with both kidney function and mental disorders using multi-comics statistical methods such as MTAG and TWAS, which may contribute to a better understanding of the underlying mechanisms." (PMID 38858783, 2024). "Therefore, PTPRJ could be a potential target for mental disorders." (PMID 38858783, 2024).
non-Hodgkin lymphoma (1 paper, 2022). Distinct from Hodgkin lymphoma both morphologically and biologically, non-Hodgkin lymphoma (NHL) is characterized by the absence of Reed-Sternberg cells, can occur at any age, and usually presents as a localized or generalized lymphadenopathy associated with fever and weight loss. "Moreover, PTPRJ is a potential tumor suppressor gene for non-small cell lung cancer (NSCC) and non-Hodgkin’s lymphoma (NHL)." (PMID 36611803, 2022).
non-small cell lung carcinoma (1 paper, 2018). A group of at least three distinct histological types of lung cancer, including non-small cell squamous cell carcinoma, adenocarcinoma, and large cell carcinoma. "Indeed, the non-small cell lung cancers (NSCLCs) of patients showing a short survival rate express the lowest and the highest levels of PTPRJ and SLC3A2, respectively." (PMID 29805737, 2018).
ovarian carcinoma (1 paper, 2022). A malignant neoplasm originating from the surface ovarian epithelium. "A variant within PTPRJ was also identified by exome sequencing and targeted testing in a mother with bilateral ovarian cancer and daughter with NHL." (PMID 36612224, 2022).
thoracic aortic aneurysm (1 paper, 2022). An aneurysm formed in the wall of the proximal portion of the descending aorta proceeding from the arch of the aorta. "A recent study reported that PTPRJ is upregulated in the aortic tissue of patients with thoracic aortic aneurysm (TAA) and could predict the presentation of TAA." (PMID 35741789, 2022).
type 2 diabetic nephropathy (1 paper, 2019). "In these preliminary discovery experiments, we first implemented the iTRAQ technique to identify plasma gelsolin, collectin-11, PTPRJ, and AKAP-7 as candidate biomarkers in type 2 IDN, which will provide a useful basis for further analysis of the pathogenic mechanism of type 2 diabetic nephropathy." (PMID 31384238, 2019).
tumor (47 papers, 2009 to 2025). "A short variant of PTPRJ, named sPTPRJ, is generated by alternative splicing, resulting in a soluble protein secreted into the supernatant by both endothelial and tumor cells." (PMID 38999976, 2024). "PTPRJ dephosphorylates the inhibitory Tyr residue of Src, leading to Src auto-phosphorylation and full activation, which can initiate tumor-associated angiogenesis." (PMID 38999976, 2024). "Protein tyrosine phosphatase receptor type J (PTPRJ) has been reported to be a tumour susceptibility gene and acts as a tumour suppressor gene during the carcinogenesis of THCA." (PMID 32626543, 2020). "Overexpression of PTPRJ is associated with inhibition of cell proliferation and migration in many tumor cells." (PMID 31384238, 2019). "Across all TCGA studies published to date (10,951 cases from 33 tumor types in the TCGA PanCancer Atlas accessed via cBioPortal), the frequency of somatic PTPRJ point mutations and/or deep deletions is low– 211/10,951 (1.9%)." (PMID 30188888, 2018). "Several lines of evidence support the tumour suppressive role of PTPRJ, as this protein tyrosine phosphatase has been implicated in the oncogenesis of breast, lung, colorectal, thyroid and meningioma cancers." (PMID 24885312, 2014). "Recently, several classical PTPs have been identified as potential tumor suppressors, including receptor PTPs such as DEP1 (densityenhanced phosphatase-1, encoded by PTPRJ), PTPκ (encoded by PTPRK) and PTPρ (encoded by PTPRT)." (PMID 25412184, 2014). "Furthermore, detection of PTPRJ loss of heterozygosity in lymphomas also supported a tumor suppressor candidacy." (PMID 36755664, 2022). "PTPRJ is located on chromosome 11p11.2 and encodes a receptor-like protein tyrosine phosphatase, whose aberrant expression plays an important role in disrupting the malignant phenotype of tumor cells." (PMID 36578050, 2022). "Furthermore, the association between low PTPRJ levels on poorer survival in the Borg-359 cohort are also suggestive of tumor suppressive behaviour." (PMID 22815804, 2012). "Markedly decreased protein levels of PTPRJ have been observed in cancer cell lines (e.g., colon, breast, pancreas, thyroid, and lung), suggesting the tumor-suppressive role of PTPRJ." (PMID 38999976, 2024). "The protein tyrosine phosphatase receptor type J (PTPRJ) exerts a negative regulatory effect on cell proliferation, migration, differentiation, and cell adhesion, and is therefore considered a tumor suppressor." (PMID 39061080, 2024). "Current studies have shown that PTPRJ expression levels are negatively regulated by tumor cell transformation." (PMID 36611803, 2022). "Given the tumor-suppressing function of PTPs such as PTPRJ, strategies to enhance PTP activity have been developed by exploiting their regulatory mechanisms, such as ligand binding or oligomerization." (PMID 36452504, 2022). "MiRNAs have been reported to regulate the gene expression of PTPRJ and thus affect tumor progression." (PMID 36578050, 2022). "This highlights the role of PTPRJ as a candidate tumor-suppressor, especially in the context of RTK-driven cancers." (PMID 36452504, 2022). "Top 10 candidates also included proteins associated with tumor progression (LAMA5, SDCBP, TENA, PTPRJ, MUC16, TAOK1; see “Discussion”)." (PMID 35241737, 2022). "DEP-1/PTPRJ is a tyrosine-specific receptor tyrosine phosphatase that is primarily known for its role as a tumor suppressor." (PMID 34884670, 2021). "In CRC, miR-155 targets protein tyrosine phosphatase receptor J-type (PTPRJ) mRNA, inhibits the anti-proliferation effects of PTPRJ, promotes the proliferation and migration of tumor cells, and activates the AKT pathway." (PMID 34305614, 2021). "Protein-Tyrosine Phosphatase Receptor Type J (PTPRJ) is a tumor suppressor that negatively regulates processes such as angiogenesis, cell proliferation and migration and is widely expressed in many cell types, including epithelial and endothelial cells." (PMID 31384238, 2019).